C22orf42 (chromosome 22 open reading frame 42)
Synonyms: dJ90G24.6
Tractability: No criterion of Open Targets' tractability assessment is met for any kind of drug.
Gene: Protein-coding gene on chromosome 22 (32,149,006 to 32,159,322, reverse strand). Ensembl gene ENSG00000205856.
Genetic constraint (gnomAD): Loss-of-function variants: 22 observed, 28.43 expected, observed/expected ratio (o/e) 0.77, 90% interval 0.55 to 1.11. The upper end of that interval is the gene's LOEUF score, 1.11, which puts it in group 4 of 6, group 1 being the genes least tolerant of losing a copy. Missense variants: 269 observed, 316.18 expected, observed/expected ratio (o/e) 0.85, 90% interval 0.77 to 0.94. Synonymous variants: 94 observed, 111.24 expected, observed/expected ratio (o/e) 0.85, 90% interval 0.71 to 1.
Homologues: Orthologues: chimpanzee C22H22orf42 (83% identical). Paralogues in human: DRICH1 (22% identical).
Diseases named in the same sentence as C22orf42 in open-access papers:
C22orf42 is named in the same sentence as 2 diseases in open-access papers, as found by Europe PMC text mining. Sharing a sentence is not in itself a finding about the gene and the disease. The quoted sentences say what the papers report.
pituitary adenomas (1 paper, 2025). "Additional genes—PHYHD1, LTBR, MYBPHL, C22orf42, PRR5, ANKDD1A, RAB13, CAMKV, KIFC3, WNT4, and STAT6—were implicated in the invasive behavior of non-functioning pituitary adenomas (NFPAs)." (PMID 39859246, 2025).
tumor (1 paper, 2019). "The DNA methylation and expression levels of PHYHD1, LTBR, MYBPHL, C22orf42, PRR5, ANKDD1A, RAB13, CAMKV, KIFC3, WNT4 and STAT6 are associated with tumor invasion, and these genes may become the potential genes for targeted therapy." (PMID 31796052, 2019).